NAT1 (N-acetyltransferase 1)
Diseases named in the same sentence as NAT1 in open-access papers (continued):
Sharing a sentence is not in itself a finding about the gene and the disease.
lobular breast carcinomas (2 papers, 2014 to 2019). "Elevated expression of N-acetyltransferase 1 (NAT1) is associated with invasive and lobular breast carcinomas as well as with bone metastasis following an epithelial-to-mesenchymal transition." (PMID 31531019, 2019). "Elevated NAT1 expression is associated with invasive and lobular breast carcinomas." (PMID 31531019, 2019).
lymph node metastasis (2 papers, 2020 to 2022). "This study constructed a prognostic model of genes related to lymph node metastasis in COAD and found that PMCH, CD1B, NAT1, NKAIN4, and LRP2 have prognostic, predictive values." (PMID 36727052, 2022). "Both positive XBP1 expression and negative NAT1 expression were significantly associated with the poorly differentiated type, larger tumor size (>3 cm), advanced TNM stage (III + IV), lymph node metastasis, invasion, and only receiving biopsy in GBC (all P < 0.05)." (PMID 32793479, 2020). "Both XBP1-positive expression and NAT1-negative expression were significantly correlated to poorly differentiated types, advanced TNM stages, lymph node metastasis, invasion, and only receiving biopsy in SC/ASC (all P < 0.05)." (PMID 32793479, 2020). "The percentage of XBP1-positive and NAT1-negative expression was significantly higher in the cases with poor differentiation, advanced tumor, nodes, and metastases (TNM) stage, lymph node metastasis, invasion, and only receiving biopsy in GBC, SC/ASC, and AC (all P < 0.05)." (PMID 32793479, 2020).
malignant melanoma (2 papers, 2018). "In melanoma, NAT1 expression increased as tissue progressed from benign to vertical growth and then metastatic disease, suggesting high levels of NAT1 are associated with a more aggressive phenotype." (PMID 29518119, 2018). "Further, al-oe-emodin inhibited cytosolic N-acetyltransferase 1 (NAT1) enzyme activity and mRNA expression in A375.S2 malignant melanoma cells in a dose-dependent manner." (PMID 30895270, 2018).
oesophageal cancer (2 papers, 2014 to 2015). "We hypothesized that NAT1 and NAT2 genetic polymorphisms may influence the risk of oesophageal cancer upon exposure to environmental carcinogens." (PMID 25886288, 2015). "Dr Matejcic concluded that NAT1 and NAT2 acetylation polymorphisms might have an important role in modifying the interaction between environmental risk factors and oesophageal cancer risk in black and mixed ancestry South Africans." (PMID 24550997, 2014). "NAT1 and NAT2 acetylation phenotypes were not independently associated with oesophageal cancer risk in both population groups." (PMID 24550997, 2014).
pancreatic carcinomas (2 papers, 2011 to 2021). "One meta-analysis found NAT1 polymorphism to be related to the risk of lung, colorectal, head and neck, bladder, and gastric carcinomas, but not with prostate, breast, and pancreatic carcinomas and non-Hodgkin’s lymphoma." (PMID 34684132, 2021).
prostate carcinoma (2 papers, 2020). A carcinoma that arises from epithelial cells of the prostate gland. "Additionally, the difference of NAT1 expression between prostate cancer and normal tissue varied from tumor grade." (PMID 32793479, 2020).
adenosquamous carcinoma (1 paper, 2020). A carcinoma composed of malignant glandular cells and malignant squamous cells. "Then, we assayed XBP1 and NAT1 expression in 215 GBCs, including 69 squamous cell/adenosquamous carcinomas (SC/ASCs) and 146 adenocarcinomas (ACs) with immunohistochemistry." (PMID 32793479, 2020).
bladder tumor (1 paper, 2015). "Studies also showed that berberine markedly decreases the activity of NAT-1 in human colon and bladder tumor cells." (PMID 26642326, 2015).
colorectal adenocarcinoma (1 paper, 2021). The most common type of colorectal carcinoma. "Besides, it has been reported that the inherited polymorphism in the acetyltransferase 1 (NAT1) gene increases the risk of colorectal adenocarcinoma." (PMID 33441161, 2021).
Crohn disease (1 paper, 2024). A gastrointestinal disorder characterized by chronic inflammation involving all layers of the intestinal wall, noncaseating granulomas affecting the intestinal wall and regional lymph nodes, and transmural fibrosis. "Although comparing the dosage of mesalazine in our study with that used in Crohn’s disease treatment is challenging due to the drug’s rapid metabolism within the bowel, mesalazine undergoes swift metabolism by intestinal N-acetyltransferase 1 (NAT1) to an inactive form, N-acetyl-5ASA." (PMID 38474043, 2024).
gallbladder cancer (1 paper, 2020). "However, the roles of XBP1 and NAT1 in gallbladder cancer (GBC) are never reported." (PMID 32793479, 2020).
gallstones (1 paper, 2020). Solid crystalline precipitates in the biliary tract, usually formed in the gallbladder, resulting in the condition of cholelithiasis. "The expression of XBP1 and NAT1 was non-significantly associated with the occurrence of gallstone in AC (all P > 0.05)." (PMID 32793479, 2020). "The rate of NAT1-positive expression was significantly higher in patients with gallstone compared with that in patients without gallstone (P = 0.041)." (PMID 32793479, 2020). "The expression of XBP1 and NAT1 was non-significantly related to the occurrence of gallstone in GBC (all P > 0.05)." (PMID 32793479, 2020). "Additionally, we found that other clinicopathological features, including tumor differentiated degree, tumor size, the occurrence of gallstone, TNM stages, and XBP1 and NAT1 expression were non-significantly different in SC/ASC and AC." (PMID 32793479, 2020).
gastroschisis (1 paper, 2024). Gastroschisis is marked by viscera protruding, without a covering sac, from the fetal abdomen on the right lateral base of the umbilicus. "Padula investigated 75 genetic variants in 20 genes and found 11 gastroschisis-associated variants in NOS3, ADD1, GNB3, ICAM1, ICAM4, ICAM5, and NAT1 genes." (PMID 39728087, 2024).
Glucose intolerance (1 paper, 2016). Glucose intolerance (GI) can be defined as dysglycemia that comprises both prediabetes and diabetes. "Treatment with NAT-1 and NAT-2 reduced the glucose intolerance as is evident from the AUC of the OGTT curve, the activity of NAT-1 being comparable to that of the standard drug metformin." (PMID 27790148, 2016).
hepatotoxicity (1 paper, 2014). Toxicity that causes injury to the liver or impairs the liver function. "The proportion of patients with NAT1 and NAT2 genes predictive of slow acetylation phenotype was not statistically significantly different between the patients who developed TMP/SMX-related hepatotoxicity and those who did not." (PMID 25184238, 2014).
hyperglycaemia (1 paper, 2016). "Further, NAT-1 exhibited a dose-response effect on hyperglycaemia." (PMID 27790148, 2016).
IgA nephropathy (1 paper, 2022). "Kidney biopsies from patients with FSGS, whose plasma induced perilipin-2 expression and lipid droplet formation in hPod (rec1 and nat1), were stained with anti-perilipin-2 antibody and compared to a healthy kidney and biopsies from patients with IgA nephropathy or membranous nephropathy." (PMID 36613637, 2022).
Klebsiella pneumonia (1 paper, 2014). An pneumonia caused by infection with Klebsiella. "Similar difference have also been observed with NAT from Klebsiella pneumonia, where NAT activity on 2-aminoflurane (substrate for NAT1 and NAT2) was found to higher as compared to PABA, which is known to be a specific substrate for NAT1." (PMID 26034680, 2014).
liver cancer (1 paper, 2023). An epithelial or non-epithelial malignant neoplasm that arises from the liver. "We focused our siRNA screen on cell migration and thereby confirmed a metastasis suppressive role for MSRA, NAT1, PPP2CB, and DLC1 in liver cancer." (PMID 38134284, 2023).
malaria (1 paper, 2025). Malaria is a serious and sometimes fatal disease caused by a parasite that commonly infects a certain type of mosquito which feeds on humans. "Genes involved in ATP metabolism (EHD1), glycolysis (GYG1), and acetyl coenzyme A metabolism (NAT1) were also enriched in symptomatic and underrepresented in asymptomatic malaria." (PMID 40830592, 2025).
medulloblastoma (1 paper, 2025). A malignant, invasive embryonal neoplasm arising from the cerebellum. "The high expression levels of CEBPBand NAT1 in tumor samples highlight their potential roles in medulloblastoma development and progression." (PMID 40104502, 2025).
orofacial clefting (1 paper, 2014). "Moreover, the overexpression of (HUMAN)NAT1 in mice provokes NTDs usually associated with folate deficiency and has complex effects on the incidence and severity of orofacial clefting." (PMID 24823794, 2014). "The chromosomal region marked by (HUMAN)NAT1 and (HUMAN)NAT2 has also been shown to influence the incidence of sporadic and teratogen-induced orofacial clefting." (PMID 24823794, 2014).
palate clefts (1 paper, 2019). "In humans, deficiency in folates, in which NAT1 is implicated, is often associated with many congenital malformations including palate clefts, and some mutations in both NAT1 and NAT2 have been associated with this condition." (PMID 31068377, 2019).
salivary gland tumors (1 paper, 2021). "We harvested the CRTC1-MAML2 fusion–induced salivary gland tumors (T1, T2) and their matched tumor-adjacent normal tissues (NAT1, NAT2), along with normal salivary gland tissues from the control nontransgene carrier littermates (N1, N2)." (PMID 33830080, 2021).
cancer (64 papers, 1998 to 2026). A tumor composed of atypical neoplastic, often pleomorphic cells that invade other tissues. "Machine learning analysis pinpointed 14 feature genes, among seven were associated with cancer (NAT1, BIRC3, EZH2, MAD2L1, ATP2A3, HMGA1, and BST2)." (PMID 41255601, 2025). "This suggests the importance of NAT1*14B in cancer risk following alkylaniline exposures, especially for those that are preferential substrates for NAT1, such as 3,4-DMA." (PMID 39766269, 2024). "Apart from its involvement in biological transformations, NAT1 has been implicated in the growth and invasion of cancer cells." (PMID 38916406, 2024). "Most of these focus on associations between NAT1*10 and/or NAT1*11 and cancer risk, two variant alleles that possess SNPs in the 3′-UTR region outside of the coding exon." (PMID 35273499, 2022). "Treatment with necrosulfonamide showed that NAT1 deficient cells switched from intrinsic apoptosis to necroptosis when treated with the anti-cancer drug cisplatin." (PMID 35918499, 2022). "Genetic polymorphisms in NAT1 or NAT2 are associated with increased cancer risk at numerous sites including urinary bladder and head and neck cancers." (PMID 35281898, 2022). "The findings from studies exploring the association of NAT1 polymorphism with other cancers and HNC are different." (PMID 34684132, 2021). "Biological marks XBP1 and NAT1 are associated with progression and prognosis of a variety of human cancer types, but their roles in GBC remain to be identified." (PMID 32793479, 2020). "More and more evidence indicates that NAT1 is closely associated with the development and progression of human cancers." (PMID 32793479, 2020). "NAT1 has also been associated with changes in cancer cell survival and invasion both invitro and invivo." (PMID 31910058, 2020). "In several cancers, the expression of NAT1 is associated with cell proliferation in vitro and with survival in vivo." (PMID 31781164, 2019). "In humans, besides their influence on the effectiveness of prescribed medications, polymorphisms at NAT2, and also at NAT1, have been associated with differential susceptibility to various cancers linked to arylamine exposure." (PMID 31068377, 2019). "NAT1 expression has been associated with the estrogen receptor and it has been proposed as a prognostic marker for estrogen receptor positive cancers." (PMID 29969986, 2018). "Arylamine N-acetyltransferase 1 (NAT1) is a drug metabolizing enzyme that has been associated with cancer cell proliferation in vitro and with survival in vivo." (PMID 29969986, 2018). "Apart from its role in biotransformation, NAT1 has also been associated with cancer cell growth and invasion." (PMID 29969986, 2018). "Human NAT1 is associated with endogenous metabolic pathways of cells and is a candidate drug target for cancer." (PMID 29950659, 2018). "NAT1*10 has been associated with higher risk of developing cancers of the breast, colon/rectum, lung, pancreas, and urinary bladder." (PMID 28359264, 2017). "Our findings suggest that further study of a role for human NAT1 in cancer susceptibility apart from the role of NAT1 in carcinogen metabolism is warranted." (PMID 28359264, 2017). "It has been shown that 4-ABP DNA adducts and mutation levels were significantly higher in cells displaying elevated NAT1 activity which emphasizes the relative importance of NAT1-catalyzed O-acetylation of N-hydroxy-4-ABP in cancer risk." (PMID 26840026, 2016). "Expression of human arylamine N-acetyltransferase I (NAT1) has been associated with various cancer subtypes and inhibition of this enzyme with small molecule inhibitors or siRNA affects cell growth and survival." (PMID 25627111, 2015). "On one hand, the NAT1 enzyme was recently reported as a biomarker of cancer, and its overexpression was found to be associated with increased resistance to chemotherapy." (PMID 22956951, 2012).
cancer (continued). "In conclusion, the current study has identified a phenotypic change in cancer cells associated with the loss of NAT1 protein." (PMID 21347396, 2011). "Increased cancer risk has been associated with functional polymorphisms that occur within the genes coding for the N-acetyltransferase enzymes NAT1 and NAT2." (PMID 9528834, 1998). "Some NAT1 variants are associated with susceptibility to cancer and birth defects." (PMID 42247510, 2026). "Consequently, NAT1 holds significant research value across various cancer types, necessitating further exploration of its underlying mechanisms." (PMID 38916406, 2024). "Associations between NAT1 genetic polymorphism with cancer risk has been reviewed." (PMID 35273499, 2022). "Genetic polymorphisms in NAT1 are linked to cancer susceptibility following exposures." (PMID 35273499, 2022). "The present study was designed to investigate whether NAT1 deficiency seen in a significant proportion of breast tumours affects anti-cancer drug response." (PMID 35918499, 2022). "However, several polymorphisms in NAT1 (coding for arylamine N-acetyltransferase 1 engaged in carcinogen metabolism and detoxification) were shown to modify the risk of various cancers." (PMID 32295079, 2020). "Because NAT1 is genetically variant, patients with high NAT1 expression may be at greater risk of aggressive cancers compared to those with low expression." (PMID 29518119, 2018). "Human arylamine N-acetyltransferase 1 (NAT1) has been associated with cancer cell growth and invasion, but the underlying molecular mechanisms remain unknown." (PMID 29518119, 2018). "NAT1 is represented on most microarray chips, so interrogation of public databases has revealed changes in NAT1 mRNA levels associated with different cancers and cancer subtypes." (PMID 25528056, 2014). "Moreover, the association with NAT1*11/NAT2*6A haplotypes was correlated to the risk of UADT cancer (OR = 1.54; P = 0.03)." (PMID 24151610, 2013). "Although less well-established, human NAT1 also exhibits genetic polymorphism and several-albeit as yet inconclusive-studies have suggested that variant NAT1 genotypes are associated with susceptibility to a number of diseases including various cancers and birth defects." (PMID 23497148, 2013). "The high frequency of NAT1 acetylators genotypes are important modulators of cancer susceptibility." (PMID 23819905, 2013). "On the other hand, early screening and detection of NAT1*14 in high-risk groups, such as smokers, may be important for Lebanese in view of the double burden of the two highest cancer incidents: lung and bladder." (PMID 22956951, 2012). "Because of the relatively high frequency of the variant NAT1 genotypes in the population, the attributable cancer risk may be high." (PMID 15563733, 2004). "Also, polymorphic variants that decrease NAT1 activity would likely have a reduced cancer risk." (PMID 28359264, 2017). "In addition, some polymorphisms in the N-acetyltransferase 1 (NAT1, one of the major hepatic phase II enzymes) are associated with rapid/slow acetylation phenotypes with altered formation of acetylamino metabolites and increased susceptibility to cancers." (PMID 18816385, 2008). "Database searches indicated that NAT1, BIRC3, EZH2, MAD2L1, ATP2A3, HMGA1, and BST2 are cancer-associated genes." (PMID 41255601, 2025). "A high frequency of NAT1 and NAT2 polymorphisms makes humans prone to cancer when exposed to aromatic and heterocyclic carcinogens." (PMID 37174036, 2023). "Apart from its role in drug metabolism, NAT1 has been shown to affect cancer cell morphology, growth and proliferation, metastasis and invasion, and cellular bioenergetics." (PMID 35918499, 2022). "The objective of the current study is to investigate functional actions of the NAT1 coding exon SNPs for ABP N-acetyltransferase and the N-OH-ABP O-acetyltransferase and to interpret these results in the context of cancer risk following ABP exposures." (PMID 35273499, 2022).